CISD1 (CDGSH iron sulfur domain 1)
Diseases named in the same sentence as CISD1 in open-access papers (continued):
Sharing a sentence is not in itself a finding about the gene and the disease.
tumor (30 papers, 2015 to 2025). "A bioinformatic study explored the ferroptosis-related lncRNA GSEC/miRNA-101-3p/CISD1 axis in LUAD, identifying upregulated genes like CISD1, PGD, and ATP5MC3 associated with advanced tumor stages and poor prognosis." (PMID 40078365, 2025). "Using GEPIA 2.0 online tools, we analyzed the mRNA expression levels of CISD1 in 33 tumor tissues compared with their corresponding normal tissues (TCGA normal tissue + GTEx normal tissues)." (PMID 40831536, 2025). "Next, we wondered how many tumor tissues showed higher mRNA expression levels of CISD1 compared with corresponding normal tissues." (PMID 40831536, 2025). "Future studies will focus on experimental validation of CISD1's role in tumor aggressiveness, stemness, and immunotherapy, and exploration of its molecular mechanisms through in vitro and in vivo experiments." (PMID 40831536, 2025). "NL-1 has been reported to be an inhibitor of CISD1 which mediates autophagy and increases NL-1 induced tumor cell death." (PMID 38918793, 2024). "In a recent study, excessive expression of iron-sulfur cluster proteins, such as CDGSH iron sulfur domain 1 (CISD1), an iron-containing export mitochondrial membrane protein desensitized tumor cells to ferroptosis." (PMID 38562992, 2023). "Considering the small number of normal samples in TCGA, we integrated the data of normal tissue in the GTEx database and the data of TCGA tumor tissues to analyze the expression differences of CISD1 in 27 different tumors." (PMID 35313629, 2022). "CISD1 expressed significantly higher in tumor tissue than that of the normal tissue, indicating poor overall survival rates." (PMID 36671422, 2022). "In this study, the RNA-seq data from Cancer Genome Atlas (TCGA) database was used to compare normal and tumor samples for CISD1 expression." (PMID 36671422, 2022). "For example, the expression of SLC7A11, FANCD2, and CISD1 was higher in tumor tissues than that in normal tissues, but ATP5MC3 was lower." (PMID 35309947, 2022). "Our findings revealed that certain FRGs (CISD1, ATP5MC3, PGD, SLC7A11, ACSL3, and FANCD2) are significantly upregulated in LUAD and that their elevated expression is associated with both advanced tumor stage and unfavorable prognosis." (PMID 35320929, 2021). "Taken together, these findings support our speculation that high CISD1 expression may suppress mitophagy, help counteract hypoxia, and maintain a growth advantage for tumor cells, while simultaneously up-regulating immune checkpoints to promote immune evasion." (PMID 40831536, 2025). "Taken together, these results suggest that CISD1 may serve as a predictive factor in determining how a tumor responds to various treatments." (PMID 40831536, 2025). "Taken together, these results suggest that CISD1 could be a potential biomarker for identifying tumors with high stemness and may serve as a therapeutic target to inhibit these aggressive tumor characteristics." (PMID 40831536, 2025). "Specifically, our in vitro results suggest that ALOX5 may be an oncogene, while ALOX12 and CISD1 may be tumor suppressor genes in PAAD." (PMID 35033072, 2022). "High expression level of CISD1 in tumor shows less pDC and NK cells penetration." (PMID 36671422, 2022). "CISD1 gene expression was evaluated between tumor bulk and adjacent tissue." (PMID 36671422, 2022). "Thus, our study provides insights into understanding the potential role of CISD1 in tumor immunology and its use as potential anticancer targets." (PMID 35313629, 2022). "Analysis of gene expression, mutation, DNA methylation, and prognostic value in LUAD revealed CISD1, ATP5MC3, PGD, SLC7A11, ACSL3, and FANCD2 to be significantly upregulated in LUAD and elevated expression of these FRGs to be associated with advanced tumor stage and poor prognosis." (PMID 35320929, 2021).
tumor (continued). "Finally, CISD1, ATP5MC3, PGD, SLC7A11, ACSL3, and FANCD2 expression was confirmed to significantly correlate with tumor mutational burden (TMB), microsatellite instability (MSI), immune cell infiltration, cellular checkpoint dysfunction, and cancer sensitivity to drugs." (PMID 35320929, 2021). "We downloaded CISD1 mRNA expression data in different human normal tissues from GTEx datasets and in different tumor tissues from TCGA datasets via the THPA online website and analyzed the CISD1 mRNA expression level." (PMID 40831536, 2025). "The mRNA expression of KEAP1, HSBP1, SAT1, CISD1, and GPX4 were significantly different between tumor and the adjacent tissues." (PMID 34692692, 2021). "Four ferroptosis driver genes FLT3, ALOX12B, ALOX15, and VDAC2, had a low CNV, and four ferroptosis suppressor genes ACSL3, CISD1, FANCD2, and SLC3A2, had a high CNV, indicating that ferroptosis was inhibited in tumor development." (PMID 34434214, 2021). "An investigation of the correlation between FRG expression and tumor stage revealed only ATP5G3, CISD1, and PGD expression to positively correlate with the LUAD stage." (PMID 35320929, 2021). "The upstream lncRNA GSEC/miRNA-101-3p regulatory axis involving CISD1, ATP5MC3, and PGD was identified to be relevant in tumor progression." (PMID 35320929, 2021). "Importantly, levels of ATP5G3, CISD1, and PGD expression were found to positively correlate with tumor stage." (PMID 35320929, 2021). "As ferroptosis plays crucial roles in both immunity and pulmonary carcinogenesis, the correlation between CISD1, FANCD2, PGD, ASCL3, ATP5MC3, and SLC7A11 expression and tumor immune infiltration in LUAD was evaluated utilizing data obtained from the TIMER database." (PMID 35320929, 2021). "The genes that regulate iron metabolisms, such as NFS1 (NFS1 cysteine desulfurase) and CISD1 (CDGSH iron–sulfur domain 1), may become novel targets for tumor-targeted therapy." (PMID 34434214, 2021). "Elevated CISD2 and CISD1 proteins have been observed in human epithelial breast cancer cells; inhibiting CISD2 and CISD1 expression results in increased iron accumulation within mitochondria, autophagy activation, and significant reduction of cell proliferation and tumor growth." (PMID 37304867, 2023).
cardiovascular diseases (3 papers, 2018 to 2024). "Moreover, ferroptosis is closely related to the development of pulmonary and cardiovascular diseases, whether CISD1 could be a key factor in the regulation of iron homeostasis and disease related potential target is worth investigating." (PMID 38918793, 2024). "Then targeting the unannotated CISD1-u might be a promising therapy for VSMC phenotypic switching and related cardiovascular diseases." (PMID 37907652, 2023).
CISD1 also shares sentences with these, for which no sentence is quoted: Huntington disease (3 papers); Wolfram syndrome 2 (3); bladder cancer (2); colon cancer (2); cystic fibrosis (2); esophageal cancer (2); gastric cancer (2); metabolic disease (2); neurodegenerative disease (2); skin cancer (2); testis cancer (2); acute lymphocytic leukemia (1); acute myeloid leukemia (1); adrenocortical carcinoma (1); Alzheimer disease (1); amyotrophic lateral sclerosis (1); bladder urothelial carcinoma (1); cervical squamous cell carcinoma (1); cervix cancer (1); cholangiocarcinoma (1); colon adenocarcinoma (1); colorectal cancer (1); diabetic cardiomyopathy (1); endometrial adenocarcinoma (1); endometrium cancer (1); glioblastoma (1); head and neck squamous cell carcinoma (1); heart diseases (1); hyperlipidemia (1); Insulin resistance (1).
A further 22 diseases each share a sentence with CISD1 in 1 paper.